IL16 (interleukin 16)
Diseases named in the same sentence as IL16 in open-access papers (continued):
Sharing a sentence is not in itself a finding about the gene and the disease.
Obesity (9 papers, 2011 to 2025). Accumulation of substantial excess body fat. "The further use of Fisher’s exact test identified obesity (p = 0.027) and high serum levels of IL-16 (p = 0.029) as significant risk factors for sarcopenia in females." (PMID 37630720, 2023). "In women, high IL-16 levels and obesity increase the risk of sarcopenia, whereas malnutrition and low IL-16 levels are risk factors in men." (PMID 37892780, 2023). "The aim of this study was to investigate IL-12p40, IL-12p70, and IL-16 in overweight adolescents and their association with anthropometrical measurements of obesity." (PMID 25710036, 2015). "Here, we tried to examine the association of IL-12p40, IL-12p70, and IL-16 with obesity in a study cohort of overweight adolescents." (PMID 25710036, 2015). "We were able to demonstrate that obesity is associated with up-regulation of several pro-inflammatory cytokines, including IL-1ra, IL-2, IL-16, MCP-1, MIG, RANTES, C5a and sICAM-1." (PMID 22748184, 2012). "Elevated IL-16 is associated with obesity-related inflammatory responses." (PMID 40671914, 2025). "Based on these results, we believe that the increased levels of IL-12p40 and IL-16 are associated with an ongoing inflammatory response in obese individuals and could lead to the development of disease conditions related to obesity." (PMID 25710036, 2015). "Therefore, it is tempting to think that IL-16 could be promoting the reduction of Hif1a, which causes a decrease in Vegf in the context of altered adipose tissue remodeling in obesity." (PMID 38544694, 2024). "The function of IL-16 in the peripheral proinflammatory immune response has been widely studied, however, its role in adipocytes in the context of obesity is unclear." (PMID 38544694, 2024). "In this study, our objective was to elucidate the significance of IL-16 in the context of obesity by examining its levels in a human cohort of patients with obesity and assessing its effect on adipocyte biology." (PMID 38544694, 2024). "Using our data from RNAseq of WAT T lymphocytes from individuals with obesity, an upregulation of IL-16 was observed in enriched pathways related to SARS-CoV-2 infection, poor prognosis, and severe symptoms." (PMID 38544694, 2024). "Mature adipocytes were co-treated with palmitate (1 mM) and IL-16 at concentrations of 1 or 10 ng/mL IL-16 for 24 h to study the impact of IL-16 in the context of obesity." (PMID 38544694, 2024). "Future studies should explore in vivo approaches to further evaluate the role of IL-16 in adipose tissue biology in obesity." (PMID 38544694, 2024). "Our results suggest a potential role of IL-16 in adipogenesis, lipid and glucose homeostasis, fibrosis, and inflammation in an obesity context." (PMID 38544694, 2024). "IL-16 gene expression was elevated in vWAT from individuals with obesity and correlated with inflammatory markers." (PMID 38544694, 2024). "IL-16 has been widely studied in the peripheral proinflammatory immune response; however, little is known about its role in adipocytes in the context of obesity." (PMID 38544694, 2024). "The results demonstrated that IL-16 expression was higher in vWAT compared with sWAT in individuals with obesity." (PMID 38544694, 2024). "In conclusion, our results demonstrate that IL-16 is induced in obesity, suggesting its involvement in adipogenesis and cellular homeostasis." (PMID 38544694, 2024). "Higher serum levels of IL-16 were observed in patients with obesity compared with normal-weight individuals, with an increase 6 months after bariatric surgery that is reverted 12 months after the intervention." (PMID 38544694, 2024). "IL-16 expression was evaluated in vWAT and sWAT from both groups, finding that IL-16 expression was increased in vWAT from individuals with obesity compared with sWAT and vWAT from normal-weight individuals (P< 0.0001)." (PMID 38544694, 2024).
Obesity (continued). "The multivariate analysis of female participants revealed that high IL-16 levels, low MNA scores, and obesity contribute to a higher risk of sarcopenia." (PMID 37630720, 2023). "IL-12p40 and IL-16 correlated significantly with anthropometrical parameters of obesity (body weight, BMI, and waist circumference)." (PMID 25710036, 2015). "Further studies are warranted in order to decode mechanisms leading to the expression of IL-12p40, IL-16, and other inflammatory factors in the context of obesity." (PMID 25710036, 2015). "Levels of IL-12p40 and IL-16 correlated also significantly with anthropometrical measurements of obesity such as weight, BMI, and waist circumference." (PMID 25710036, 2015). "Obesity induced adipose tissue cytokine expressions, the most highly upregulated cytokines being IL-1ra, IL-2, IL-16, MCP-1, MIG, RANTES, C5a, sICAM-1 and TIMP-1." (PMID 22748184, 2012). "The addition of 10 ng/mL IL-16 blunted palmitate-induced lipid accumulation and glycerol release, suggesting that IL-16 may impair lipolysis, leading to adipocyte hypertrophy in an obesity context." (PMID 38544694, 2024). "Therefore, we aimed to study the role of IL-16 in obesity, evaluating its effect on adipocyte biology." (PMID 38544694, 2024). "In our cohort, IL-16 expression was increased in vWAT from individuals with obesity compared with sWAT from individuals with obesity and vWAT and sWAT from normal-weight individuals; similarly, obese animal models presented higher levels of IL-16 than lean controls." (PMID 38544694, 2024). "In addition, IL-16 serum levels were higher in patients with obesity compared with normal-weight individuals, increased at 6 months after bariatric surgery, and at 12 months after surgery decreased to levels similar to before the intervention." (PMID 38544694, 2024). "This would imply that IL-16 might play a crucial role in maintaining proper adipocyte biology in the context of obesity." (PMID 38544694, 2024). "It is tempting to think that IL-16 could play a role in adipogenesis in obesity to promote fibrosis and alter lipid storage in adipocytes." (PMID 38544694, 2024). "This led to the assumption that MNA and obesity may correlate in females with high IL-16 serum levels." (PMID 37630720, 2023). "Both drugs have proven to be effective in reducing inflammation through various pathways: they reduced CRP levels in patients with obesity, while colchicine was also effective in reducing IL‐6, IL‐16, resistin, complement proteins C5a and C9, and the activity of the COX‐2 enzyme." (PMID 35837843, 2022). "Thus, elevated IL-16 may also lead to the development of disease conditions that are related to obesity." (PMID 37630720, 2023). "One could speculate that the IL-12p40/IL-16 axis might be a more forefront proinflammatory signaling pathway in the earlier stages of obesity related disease conditions as they were likely present in our cohort of adolescents compared to the inflammatory milieu found in adult patients." (PMID 25710036, 2015). "We aimed to study the levels of IL-16 in WAT derived from sWAT and vWAT depots of humans with obesity and the role of this cytokine in palmitate-exposed 3T3-L1 adipocytes." (PMID 38544694, 2024). "The effect of IL-16 on inflammation, glucose and lipid metabolism, and remodeling, given their involvement in WAT during obesity, was analyzed." (PMID 38544694, 2024). "Notably, IL-12p40 and IL-16 but not IL-12p70 are elevated in overweight adolescents, correlating with different anthropometrical parameters of obesity." (PMID 25710036, 2015).
psoriasis (9 papers, 2016 to 2025). An autoimmune condition characterized by red, well-delineated plaques with silvery scales that are usually on the extensor surfaces and scalp. "Further, we quantified the mediating effects of genetically-predicted ESAM and Il-16 among the effects of psoriasis on AMI risk." (PMID 40419871, 2025). "The multivariable MR mediation analysis was used to evaluate the degree to which these 2 traits (ESAM and IL-16) mediated the effects of genetically-predicted psoriasis on AMI risk." (PMID 40419871, 2025). "Authors found that IL-16 levels significantly correlate to the disease activity of psoriasis, the duration of which is associated to spleen volume." (PMID 31547124, 2019). "Furthermore, the potential mediating roles of ESAM and IL-16 in psoriasis-induced AMI susceptibility are yet to be explored in depth." (PMID 40419871, 2025). "The targeted intervention of ESAM and IL-16 might help decrease the risk of AMI in psoriasis patients." (PMID 40419871, 2025). "Specifically, we employ MR mediation analysis to assess whether ESAM and IL-16 mediate the relationship between psoriasis and AMI risk." (PMID 40419871, 2025). "From this, we inferred that specifically receiving too much TNF signaling and sending too much IL16 signaling may make IS CD8+ T cells a pathogenic subpopulation in psoriasis." (PMID 38915827, 2024). "This study is the first report on IL-16 gene polymorphism among psoriasis patients." (PMID 27788245, 2016). "In conclusion, our data revealed an association between circulating IL-16 and severity of psoriasis which indicates that this cytokine could serve as a potential marker of disease activity." (PMID 27788245, 2016). "In psoriasis, a common immune-mediated skin disease, serum levels of IL-16 correlate with disease severity measured by psoriasis area and severity index (PASI)." (PMID 40529362, 2025). "MR has been successfully employed to identify mediating pathways in various diseases; however, to the best of our knowledge, the causal relationships between psoriasis, ESAM, IL-16, and AMI have yet to be explored using this method." (PMID 40419871, 2025). "Two-sample MR analyses were conducted to assess the causal effects of psoriasis, ESAM, and IL-16 on AMI risk." (PMID 40419871, 2025). "This study aims to fill this critical knowledge gap by evaluating the causal effects of psoriasis, ESAM, and IL-16 on the risk of AMI through the MR framework." (PMID 40419871, 2025). "Genetic liability to psoriasis is correlated with a higher risk of AMI, which is partially mediated by ESAM and IL-16." (PMID 40419871, 2025). "The serum levels of IL-16 were significantly elevated in patients with psoriasis compared to unaffected individuals." (PMID 40731810, 2025). "IκBζ, a mediator of IL17-A-induced transcriptome activity, is known as a key regulator of specific psoriasis-associated genes that include DEFB4, S100A7, and IL-16." (PMID 34445513, 2021). "In one study, the results show that the use of propranolol enhances higher gene expression of Interleukin-16 (IL-16) and other growth factors, having the ability to control, or in this case exacerbate, the immunologic reactions seen in psoriasis." (PMID 32766006, 2020). "In our study, patients with psoriatic arthritis and individuals who received biological therapies were excluded to provide a clearance of psoriasis group and avoid potential influence of these factors on IL-16 levels." (PMID 27788245, 2016). "The authors suggested the difference between psoriasis and AD in a Th1/Th2 balance as one of the reasons for the disparity in IL-16 serum levels." (PMID 27788245, 2016). "Serum levels of IL-16 were significantly increased in patients with psoriasis compared with unaffected subjects." (PMID 27788245, 2016). "MR mediation analysis was used to determine whether ESAM and IL-16 mediate the effect of psoriasis on AMI." (PMID 40419871, 2025).
psoriasis (continued). "Additionally, the proportion of the effects of genetically-predicted psoriasis mediated by genetically-predicted IL-16 was 16.1% (95% CI 5.3%–26.8%)." (PMID 40419871, 2025). "Authors suggested that IL-16 could be seen as “psychocutaneous” cytokine and could link depression in psoriasis patients." (PMID 40529362, 2025). "The pleiotropic impact of IL-16 on immune system cells and its association with CD4+ lymphocytes suggest that this cytokine may be involved in the pathogenesis of psoriasis." (PMID 40731810, 2025). "The MR analysis supported that psoriasis, ESAM, and IL-16 are risk factors for AMI." (PMID 40419871, 2025). "However, the detailed mechanism of IL-16 impact on the development and progression of psoriasis requires clarification due to its potential cooperation and interdependencies with other proinflammatory cytokines and immune system cells." (PMID 27788245, 2016). "The pleiotropic impact of IL-16 on immune system cells and its association with CD4+T cells suggest that this cytokine might be involved in the pathogenesis of psoriasis." (PMID 27788245, 2016). "Additionally, ESAM and IL-16 play an intermediary role in psoriasis complicated with AMI." (PMID 40419871, 2025). "Moreover, the research revealed significant positive correlation between IL-16 levels in serum and clinical severity of psoriasis which indicates that this cytokine could serve as a potential marker of disease activity." (PMID 27788245, 2016). "The proportion of the effects of genetically-predicted psoriasis mediated by genetically-predicted ESAM, IL-16, and both ESAM and IL-16 was estimated as 24.8% (95% CI: 8.3%–41.2%), 16.1% (95% CI: 5.3%–26.8%), and 26.9% (95% CI: 6.3%–47.6%), respectively." (PMID 40419871, 2025). "A total of 8 SNPs were correlated with psoriasis, 3 SNPs were correlated with ESAM, and 3 SNPs were correlated with IL-16, as identified at a genome-wide significance level of P < 5 × 10−8." (PMID 40419871, 2025). "The proportion of the effects of genetically-predicted psoriasis mediated through genetically-predicted ESMA and IL-16 was 24.8% (95% CI 8.3%–41.2%) and 16.1% (95% CI 5.3%–26.8%), respectively." (PMID 40419871, 2025). "First, the GWAS datasets of psoriasis, AMI, and ESAM contain male and female samples, while the GWAS dataset of IL-16 lacks gender information." (PMID 40419871, 2025). "Additionally, IL-16 serum levels exhibited a positive correlation with the PASI and Body Surface Area (BSA), and were notably higher in patients with moderate-to-severe psoriasis." (PMID 40731810, 2025). "The genetic liability to psoriasis (odds ratio [OR]: 1.00078; 95% confidence interval [CI]: 1.00008–1.00148; P = .028479), ESAM (OR: 1.00208; 95% CI: 1.00019–1.00397; P = .031089), and IL-16 (OR: 1.00118; 95% CI: 1.00009–1.00227; P = .033826) were associated with higher AMI risks." (PMID 40419871, 2025). "Moreover, IL-16 serum levels positively correlated with PASI and BSA (r = 0.34, P = 0.01) and were significantly higher in the group of patients with moderate to severe psoriasis." (PMID 27788245, 2016). "Therefore, targeted intervention of IL16 signaling emitted by IS CD8+ T cells, as well as interfering with the reception of TNF signaling by IS CD8+ T cells, may be potential therapeutic targets for psoriasis." (PMID 38915827, 2024). "Interleukin 16 (IL-16) has been described as a significant cytokine involved in the recruitment of CD4+ cells during inflammation; however, its potential role in psoriasis has not been defined." (PMID 27788245, 2016). "Furthermore, the IL-16 mRNA levels within psoriatic lesions positively correlated with the levels of CD4 mRNA, but not with Psoriasis Area and Severity Index." (PMID 27788245, 2016).
atherosclerosis (8 papers, 2015 to 2025). A disease characterized by the build-up of fatty material and calcium deposition in the arterial wall resulting in partial or complete occlusion of the arterial lumen. "On the other side, elafin was also linked to atherosclerosis development alongside other inflammatory markers like E-selectin, Chemokine CC motif ligand 7 (CCL7), IL16." (PMID 40969761, 2025). "By contrast, there are also reports suggesting that IL-16 may possess protective effects against other inflammatory disorders, such as atherosclerosis." (PMID 35113938, 2022). "Based on this finding, we assumed that IL-16 might play a critical role in the development of vascular plaque lesion formation, which was attributed to vascular diseases such as atherosclerosis and re-stenosis." (PMID 26544695, 2015). "It has been found that AD patients have increased levels of markers of atherosclerosis including fractalkine/CX3CL1, CCL8, M-CSF, and HGF, as well as increased levels of mediators of atherosclerosis such as E-selectin or PI3/elafin, CCL17, and IL-16, which are proportional to SCORAD." (PMID 34551806, 2021). "However, inflammatory mediators involved in atherosclerosis development (E-selectin, CCL7, IL16, PI3/elafin) were significantly correlated with AD severity/SCORAD, but not with BMI, strongly suggesting the contribution of cutaneous disease to cardiovascular morbidity." (PMID 28821884, 2017). "Several atherosclerosis mediators in serum (e.g. E-selectin, PI3/elafin, CCL7, IL-16) correlated with SCORAD, but not BMI." (PMID 28821884, 2017).
myocarditis (8 papers, 2022 to 2025). Myocarditis is a condition that is characterized by inflammation of the heart muscle (myocardium). "In one case report, patients with vaccine-induced myocarditis had increased levels of interleukin 1 (IL-1) receptor antagonist, interleukin 5 (IL-5), and interleukin 16 (IL-16)." (PMID 36006288, 2022). "This study obtained left ventricular endomyocardial biopsies from both natural COVID-19 infection and vaccination myocarditis, with IFN-γ being predominant in natural infection, while IL-16 and IL-18 were in vaccination." (PMID 40573879, 2025). "In intercellular communication in this study, the increase in IL-16 signal outflow and LIGHT signal inflow were unique features of classical monocytes in BNT162b2-myocarditis stage." (PMID 36225942, 2022). "The patients with myocarditis also showed high levels of IL-1 receptor antagonist (interleukin 1), IL-5, and IL-16 but no proinflammatory cytokines, for example, IL-6, tumor necrosis factor, IL-1B, IL-2 or interferon-γ." (PMID 36498573, 2022). "In addition, IL-16 enhances the secretion of inflammatory cytokines such as IFN-γ, IL-10, IL-16, TNF-α, and IL-15 by monocytes and mature macrophages, which promotes the development of myocardial inflammation and thus plays an indirect role in promoting the development of myocardial fibrosis." (PMID 40881586, 2025).
ovarian carcinoma (8 papers, 2015 to 2024). A malignant neoplasm originating from the surface ovarian epithelium. "Meanwhile, a study evaluated the relationship between pre-diagnostic IL-16 serum levels and prostate cancer risk in 932 Caucasian cases and 942 controls in the Prostate, Lung, Colorectal, and Ovarian Cancer Screening Trial." (PMID 36733309, 2023). "IL-16 has also been shown to be associated with malignancies including leukemia and ovarian cancer development and progression." (PMID 30596106, 2018). "It was shown that IL-16 expression and serum abundance increases from healthy to benign tumors to early and ultimately to late stages of ovarian cancer and is positively correlated with tumor-associated microvessels." (PMID 27665539, 2016). "Single nucleotide polymorphisms (SNPs) of the IL-16 gene have been reported to influence the risk of several cancers, but their role in ovarian cancer (OC) has not been studied." (PMID 39408600, 2024). "In addition, we examined changes in nuclear expression of IL-16 expression with regards to exposure to follicle-stimulating hormone (FSH) by in vitro cell culture assays with human ovarian cancer cells." (PMID 35497879, 2022). "We observed the association of SUCNR1 expression with interleukins, including IL1B (cor = 0.473, p = 2.86e-18), IL7 (cor = 0.39, p = 1.78e-12), IL16 (cor = 0.508, p = 2.66e-21), and IL18 (cor = 0.348, p = 4.67e-10), in ovarian cancer." (PMID 33062639, 2020). "Similarly, significantly higher expression of IL-16 (1.66 × 106 ± 4.8 × 103 in 20,000 μm2 area of the blot) (P < 0.001) was detected in the nuclear fraction of OVCAR3 ovarian cancer cells." (PMID 35497879, 2022).